TWIST1 (twist family bHLH transcription factor 1)
Diseases named in the same sentence as TWIST1 in open-access papers (continued):
Sharing a sentence is not in itself a finding about the gene and the disease.
lung cancer (continued). "Immunoblot analysis also shows that TGF‐β‐induced upregulation of EMT‐associated molecules, including N‐cadherin, Snail, Twist1, and ZEB1, was abrogated by ProT overexpression in A549 and H1299 human lung cancer cells." (PMID 40259641, 2025). "For example, in lung cancer, JPX/miR-33a-5p/Twist1 regulatory axis promotes the occurrence and metastasis of lung cancer by activating Wnt/β-catenin signaling pathway." (PMID 38811958, 2024). "High YAP, TWIST1, SMA3 expression, and NSE level as effective molecular biomarkers is associated with a favorable prognosis of lung cancer." (PMID 38589525, 2024). "As an inhibitor of TWIST1, harmine can inhibit the expression and result in the degradation of TWIST1; it was identified as a first-in-class TWIST1 inhibitor with marked antitumor activity in oncogene-driven non–small cell lung cancer." (PMID 39024569, 2024). "High YAP, TWIST1, SMA3 expression, and NSE level are associated with a favorable prognosis for lung cancer." (PMID 38589525, 2024). "A previous study demonstrated that TWIST1 increases stemness of lung cancer cells and promotes the occurrence and progression of NSCLC." (PMID 37422632, 2023). "N-cadherin expression, another hallmark of EMT, is reduced in Twist1 knockdown NSCLC cells, leading to the inhibition of apoptosis and invasive behavior in lung cancer cells." (PMID 37495969, 2023). "The interaction between TCF4 and TWIST1 upregulated PTHLH expression in lung cancer cells in response to TGFβ1 stimulation." (PMID 35406121, 2022). "The interaction between TCF4 and TWIST1 promotes lung cancer growth, metastasis, and cachexia by upregulating the expression of PTHLH and EMT-related genes." (PMID 35406121, 2022). "The results revealed that TP expression level was significantly and positively correlated with Twist1 expression in lung cancer cells." (PMID 36059624, 2022). "JPX regulated tumorigenesis and metastasis via JPX/miR-33a-5p/Twist1 axis and activated Wnt/β-catenin signaling in lung cancer." (PMID 36494339, 2022). "It has been found that lncRNA JPX promoted the metastasis of lung cancer via sponging the miR-33a-5p, up-regulated Twist1 expression, led to activating Wnt/β-catenin signaling." (PMID 35860557, 2022). "One previous study that employed a Kras-induced lung cancer transgenic mouse model found that Twist1 inhibited cell senescence, thereby accelerating and maintaining the tumorigenic effects of mutant Kras genes." (PMID 35052775, 2022). "A recent study proved that lncRNA JPX promotes lung cancer progression via modulating miR-33a-5p/TWIST1 axis." (PMID 34224315, 2021). "A long non-coding RNA, JPX, and Twist1 transcription factor are up-regulated in lung cancer and induce EMT via inhibition of miR-33a-5p and activation of Wnt/β-catenin signaling." (PMID 34660694, 2021). "In lung cancer, high promoter methylation is actually correlated with low Twist1 expression, for example." (PMID 34572796, 2021). "In this study, we found that downregulation of miR-101-3p in CAFs upregulated the expression of MMP9 and Twist1 in lung cancer cells." (PMID 34977016, 2021). "It was found that Twist1 was highly expressed in lung cancer tissues compared to that in adjacent tissues." (PMID 31941509, 2020). "Our results demonstrate that deubiquitinase USP4 promotes lung cancer cell stemness via upregulation of Twist1, Oct4 and Sox2 expression." (PMID 32549341, 2020). "Clinical analysis by Kaplan–Meier dataset showed that lung cancer patients with high USP4 or Twist1 levels exhibited poor overall survival (OS)." (PMID 32549341, 2020). "Pearson’s correlation analysis showed that the JPX expression was positively correlated with Twist1 in lung cancer patients." (PMID 31941509, 2020). "Activation of TGF-β signaling upregulates Twist1 expression, which in turn promotes lung cancer stemness." (PMID 32549341, 2020). "Together, our findings demonstrate that USP4 deubiquitinates and stabilizes Twist1 protein to promote lung cancer stemness." (PMID 32549341, 2020).
lung cancer (continued). "Together, these results demonstrate that Twist1 is a critical downstream effector in USP4-induced lung cancer stemness." (PMID 32549341, 2020). "Our data indicate that USP4 stabilizes Twist1 to promote lung cancer cell stemness, which prompted us to verify the clinical relevance of USP4–Twist1 in human lung cancer." (PMID 32549341, 2020). "Conversely, ectopic expression of USP4 significantly enhances lung cancer cell stemness, which is effectively rescued by simultaneous silencing of Twist1." (PMID 32549341, 2020). "It has been reported that lncRNA JPX/miR-33a-5p/Twist1 axis regulates tumorigenesis and metastasis of lung cancer by activating Wnt/β-catenin signaling." (PMID 32943989, 2020). "Herein, we show that USP4 is critically important in promoting lung cancer stemness via stabilizing Twist1 expression." (PMID 32549341, 2020). "RT-qPCR and western blotting were conducted to detect the expression levels of lncRNA JPX and Twist1 in lung cancer cell lines and tissues." (PMID 31941509, 2020). "The impact of JPX on Twist1 expression, cell growth, invasion, apoptosis, and in vivo tumor growth were investigated in lung cancer cells by western blotting, rescue experiments, colony formation assay, flow cytometry, and xenograft animal experiment." (PMID 31941509, 2020). "In the present study, we identified that JPX, an upregulated lncRNA in lung cancer, acted as a ceRNA for Twist1 through binding with miR-33a-5p." (PMID 31941509, 2020). "The results indicate that the JPX/miR-33a-5p/Twist1 axis regulates lung carcinoma by activating Wnt/β-catenin signaling, suggesting a therapeutic potential for lung cancer treatment." (PMID 31941509, 2020). "The present work demonstrated that lncRNA JPX, miRNA-33a-5p, and Twist1 constituted a ceRNA network to regulate lung cancer growth and metastasis." (PMID 31941509, 2020). "It has been reported that EMT-associated transcriptional factors, including Twist1, Snail, Slug and ZEB1, play a critical role in lung cancer stemness." (PMID 32549341, 2020). "Since studies have shown that miR-33a-5p negatively regulates its target gene, Twist1, we aimed to further investigate the relationship between JPX and Twist1 in lung cancer." (PMID 31941509, 2020). "Twist1 was reported to play a pivotal role in malignant progression and metastasis of tumor such as blood cancer, colorectal cancer and lung cancer." (PMID 27793033, 2016). "We therefore transduced the human lung carcinoma cell line A549 with the Twist1-ER construct (A549-Twist1-ER)." (PMID 27105506, 2016). "We examined the difference in protein expression of Twist1 between human lung cancer and paracancerous tissues from TMA." (PMID 26360779, 2015). "We found that the overexpression of Twist1 in lung cancer tissues was significantly higher than in corresponding paracancerous tissues." (PMID 26360779, 2015). "Further data analysis using gene expression omnibus repository showed that Twist1 gene expression was slightly (approximately 1.1 fold) but significantly increased in tumor tissues from lung cancer patients compared to adjacent normal tissues." (PMID 26360779, 2015). "As an example, the suppression of mTOR activity and the decrease of mTOR phosphorylation have been observed in lung cancer H1299 cells after Twist1 knockdown." (PMID 26360779, 2015). "For example, knockdown of Twist1 enhanced cell death induced by arsenic trioxide- and ionizing radiation in lung cancer cells." (PMID 25760076, 2015). "A better understanding of Twist1′s roles in lung cancer progression is likely to have important clinical implications for both prognostic prediction and therapeutic targeting." (PMID 26360779, 2015).
lung cancer (continued). "The functional roles of Twist1 in lung cancer cell lines were evaluated by small interfering RNA-mediated depletion of the protein followed by analyses of cell apoptosis and invasion." (PMID 23626784, 2013). "Depletion of Twist1 induced apoptosis, inhibited invasion and led to the reduction of N-cadherin expression in lung cancer cells." (PMID 23626784, 2013). "The aim of this study was to evaluate the clinical relevance of Twist and N-cadherin expression in NSCLC, and the effects of Twist1 knockdown on lung cancer cells." (PMID 23626784, 2013). "In this study, cell invasion assays showed that Twist1 knockdown blocked the invasion of lung cancer A549 and LTE cells, suggesting that Twist1 had an important effect on cell invasion." (PMID 23626784, 2013). "The following miRNAs were tested for their potential to repress Twist1 translation in the human lung carcinoma cell line H1299: miR-33, miR-145a, miR-151, miR-326, miR-337, miR-361, miR-378a, miR-381, miR-409 and miR-543." (PMID 23741524, 2013). "Together these data demonstrate that TWIST1 is commonly overexpressed in human lung cancer and that our KrasG12D-Twist1 mouse models do reflect human lung cancer." (PMID 22654667, 2012). "The generality of our results using different cell types and across species suggest TWIST1 is a potential therapeutic target in KRAS mutant lung cancers." (PMID 22654667, 2012). "Six out of the 7 datasets, as well as aggregate analysis of all 7 datasets demonstrated TWIST1 overexpression in lung cancers (p = 0.04 for aggregate)." (PMID 22654667, 2012). "The consequences of knocking down TWIST1 using shRNA technology was tested in human KRAS mutant H460 lung cancer cells." (PMID 22654667, 2012). "The relevance of TWIST1 as a potential therapeutic target in human lung cancers was evaluated by examining public gene expression microarray datasets." (PMID 22654667, 2012). "Importantly, regardless of whether there is an exclusive association between KRAS mutation and TWIST1 overexpression in human lung cancer cells, the data presented strongly support that TWIST1 upregulation in KRAS mutant lung cancer represents a novel and particularly promising therapeutic target." (PMID 22654667, 2012). "We also found that LSD1 is up-regulated in lung carcinomas and that its level of expression is negatively correlated with that of AcH3K9, Twist1 and N-cadherin, and positively correlated with that of E-cadherin." (PMID 22493729, 2012). "MiR-762, MST1, LATS2, YAP mRNA and protein, TWIST1, and SMAD3 may be effective diagnostic biomarkers in both lung cancer patients and chronic inflammatory patients." (PMID 38589525, 2024). "MiR-762, MST1, LAT2, YAP mRNA and protein, TWIST1, SMAD3 may be effective diagnostic biomarkers in both lung cancer patients and chronic inflammatory patients." (PMID 38589525, 2024). "The observed significant overexpression of TWIST1 and positive correlation with YAP1 in both chronic inflammatory patients and lung cancer patients may be attributed to forced expression of YAP1 that elevated TWIST1 mRNA and protein." (PMID 38589525, 2024). "However, limited research has been conducted on the mechanisms responsible for regulating TWIST1 stability in lung cancer." (PMID 37422632, 2023). "Similarly, RUNX2 is a coregulator of three TFs (E2F3, FHL2, and TWIST1) that also appear in the NSCLC lung cancer regulatory network." (PMID 36551878, 2022). "However, it is not fully understood which stimuli and signaling cascades fine-tune TCF4- and TWIST1-mediated EMT in lung cancer." (PMID 35897813, 2022). "TWIST1 expression was found increased in lung cancer tissue." (PMID 34262872, 2021). "Collectively, the data indicated that JPX and Twist1 were coordinately upregulated in lung cancer." (PMID 31941509, 2020). "High expression of both USP4 and Twist1 was significantly associated with gene signatures of Notch and TNF signaling, suggesting that Twist1 may play a role in USP4-mediated lung cancer stemness." (PMID 32549341, 2020).
lung cancer (continued). "Twist1 was highly expressed in lung cancer cells, which was consistent with JPX expression." (PMID 31941509, 2020). "Furthermore, we show that USP4 expression is elevated in human lung cancer specimens and is positively correlated with Twist1 expression." (PMID 32549341, 2020). "Twist1 expression was verified in 95 pairs of lung cancer tissues and adjacent tissues." (PMID 31941509, 2020). "In addition, USP4 expression is elevated in human lung cancer specimens and is positively correlated with Twist1 expression." (PMID 32549341, 2020). "In addition, HR23A protein, a poly-ubiquitin chain carrier, targets and degrades Twist1 to inhibit lung cancer stemness." (PMID 32549341, 2020). "As expected, miR-33a-5p was negatively correlated with Twist1 in lung cancer patients." (PMID 31941509, 2020). "Methylated Twist1 (Arg-34), as such, could also emerge as a potential important biomarker for lung cancer." (PMID 25847239, 2015). "On the other hand, a limited sample size has been used in the present study, and a future study using a larger sample from different histologic subtypes of lung cancer is needed to confirm the observed relationship between Twist1 and clinicopathological parameters." (PMID 26360779, 2015). "Twist1 could inhibit apoptosis and promote the invasion of lung cancer cells, and depletion of Twist1 in lung cancer cells led to inhibition of N-cadherin expression." (PMID 23626784, 2013). "The suppression of TWIST1 in human lung cancer cells also induced cellular senescence." (PMID 22654667, 2012). "We conclude that TWIST1 may be an effective target for “pro-senescence” therapy for human lung cancers." (PMID 22654667, 2012). "Finally, we validate that knocking down endogenous TWIST1 in human lung cancer cell lines in vitro and in vivo also results in activation of senescence." (PMID 22654667, 2012). "We found that TWIST1 is commonly overexpressed in human lung cancers." (PMID 22654667, 2012). "This hypothesis will be further explored in lung cancer through introduction of our inducible Twist1 construct into other relevant transgenic models of lung tumorigenesis." (PMID 22654667, 2012). "Importantly, through the transcriptional analysis of over 500 human tumors, human TWIST1 was found to be frequently overexpressed and hence highly relevant to primary human lung cancers." (PMID 22654667, 2012). "Our results dramatize that suppression of TWIST1 may be an effective pro-senescence therapy for human lung cancer." (PMID 22654667, 2012). "The range of relative TWIST1 overexpression observed by qPCR in our 164 primary human lung cancer samples (range 3–536 fold TWIST1 overexpression) was similar to the Twist1 overexpression observed in our mouse KrasG12D-Twist1-induced lung tumors (range 5–960 fold Twist1 overexpression, n = 6)." (PMID 22654667, 2012). "To examine whether Twist1 inhibition could be a viable therapeutic target in vivo for Kras mutant autochthonous lung cancers, we generated mice in which only Twist1 expression was doxycycline-dependent." (PMID 22654667, 2012). "A previous study demonstrated that EMT is involved in the process of metastatic dissemination to the brain, and the EMT driver genes that were upregulated in our study (SOX10, TWIST1, CDH2) may have potential as biomarkers in risk stratification for BM in suspected early-stage lung cancer." (PMID 37139160, 2023). "Moreover, we proved that TWIST1 may be a potential target to inhibit the EMT process of lung cancer, and hope to explore a new combined medication strategy through the compatibility study of active compounds in herbal extracts." (PMID 35222014, 2021). "As ID1 and TWIST1 share the binding domain of TCF4, PGC1α knock down-driven ID1 loss could not interfere with the TCF4-TWIST1 complex, and thus, induced EMT potential in the process of lung cancer metastasis." (PMID 33917757, 2021).
lung cancer (continued). "However, whether Twist1 participates in the Wnt/β-catenin pathway directly or indirectly, and whether JPX affects Twist1 expression or regulates other pathways through RNA-binding proteins to promote lung cancer development remain unclear." (PMID 31941509, 2020). "Interestingly, JPX and Twist1 were coordinately upregulated in lung cancer tissues and cells." (PMID 31941509, 2020). "Importantly, our results showed clear clinical relevance, supported by the observations that expression of USP4 and Twist1 is positively correlated in lung cancers and that high expression of USP4/Twist1 is associated with poor overall survival in lung adenocarcinoma patients." (PMID 32549341, 2020). "In lung cancer, it has a positive correlation with pathology stage, poor prognosis, and lymph node metastasis, it promotes ovarian cancer progression and chemoresistance to cisplatin and paclitaxel via activating NF‐KB, and it promotes the expression of TWIST1, MCL1(Wu, Huang, Chang, & Chou, 2017)." (PMID 30746900, 2019). "In addition, the expression of C-MYC, Cyclin D1, Bcl-2, Bcl-xL, COX-2, TWIST1, and MMP2, which are associated with NF-κB signaling, was analyzed to better understand the NF-κB pathways involved in inhibiting lung cancers and was obviously decreased by 160 μM EGCG." (PMID 31777584, 2019). "Moreover, methylated Twist1 (Arg-34), as such, could also emerge as a potential important biomarker for lung cancer." (PMID 25847239, 2015). "Notably, TWIST1 was found to be overexpressed in a majority of human lung cancer samples we tested." (PMID 22654667, 2012). "In order to investigate whether TWIST1 could determine morphological changes in EGFR mutated tumors we analyzed the effect of TWIST1 expression in vitro and showed that in EGFR mutated lung cancer cells, EGF pathway stimulation and TWIST1 cooperated to induce an EMT and the associated cell mobility." (PMID 22272264, 2012). "Nuclear prothymosin α inhibits epithelial‐mesenchymal transition (EMT) in lung cancer by increasing Smad7 acetylation and competing with Smad2 for binding to SNAI1, TWIST1, and ZEB1 promoters." (PMID 40259641, 2025). "Our findings suggest that five genes (SETDB1, TWIST1, HDAC1, SP1, and GRIA2) are likely involved in the dystropic relationship observed between Huntington’s disease and non–small cell lung cancer." (PMID 40843670, 2025). "On one hand, TWIST1 directly participates in the EMT process by regulating E-cadherin and other related proteins, thereby promoting EMT in lung cancer cells." (PMID 40304000, 2025). "PRMT1-mediated methylation of twist-related protein 1 (TWIST1) induces EMT, characterized by reduced E-cadherin expression and increased N-cadherin expression, thereby promoting migration and invasion of lung cancer cells." (PMID 38525426, 2024). "This study aimed to evaluate the possible correlation between miR-762, the Hippo signaling pathway, TWIST1, and SMAD3 in patients with lung cancer, as well as patients with chronic inflammatory diseases." (PMID 38589525, 2024). "As such, we have established that TWIST1 is a critical downstream target of the HGF/MET pathway as it was required both in vitro and in vivo for HGF/MET-driven lung cancer." (PMID 38485737, 2024). "Accordingly, this study aimed to evaluate the possible correlations between miR-762, Hippo signaling pathway, TWIST1, and SMAD3 in patients with chronic inflammatory diseases as well as lung cancer patients." (PMID 38589525, 2024). "The relative expression of miR-762, MST1, LATS2, YAP, TWIST1, and SMAD3 was determined in 50 lung cancer patients, 30 patients with chronic inflammatory diseases, and 20 healthy volunteers by real-time PCR." (PMID 38589525, 2024). "NSE protein is superior to YAP protein followed by miR-762, MST1, TWIST1, YAP gene, LATS2, and SMAD3 for the prediction of lung cancer." (PMID 38589525, 2024).